LINC00933 (long independently transcribed non-coding RNA 933)
Gene: Transcribed unprocessed pseudogene on chromosome 15 (84,570,924 to 84,578,124, forward strand). Ensembl gene ENSG00000259728.
Diseases named in the same sentence as LINC00933 in open-access papers:
LINC00933 is named in the same sentence as 7 diseases in open-access papers, as found by Europe PMC text mining. Sharing a sentence is not in itself a finding about the gene and the disease.
LINC00933 shares sentences with these, for which no sentence is quoted: attention deficit-hyperactivity disorder (1 paper); autism spectrum disorder (1); bipolar disorder (1); generalized anxiety disorder (1); obsessive-compulsive disorder (1); schizophrenia (1); unipolar depression (1).